ARID1B (AT-rich interaction domain 1B)
Diseases named in the same sentence as ARID1B in open-access papers (continued):
Sharing a sentence is not in itself a finding about the gene and the disease.
Cognitive impairment (11 papers, 2012 to 2024). Abnormal cognition is characterized by deficits in thinking, reasoning, or remembering. "This miRNA was demonstrated to be associated with behavioral and cognitive impairments by regulating the expression of AT-Rich Interaction Domain 1B (ARID1B) gene." (PMID 38474035, 2024). "Additional functional studies including a systematic search for ARID1B target genes may show how haploinsufficiency of ARID1B predispose to CC defects and to an array of cognitive defects, including severe speech defects." (PMID 21801163, 2012). "Arid1b+/− mice showed a deficit in novel object recognition, which aligns with cognitive deficits previously found." (PMID 33757588, 2021). "Our previous study has shown that Arid1b haploinsufficient (Arid1b+/−) mice exhibit social, emotional, and cognitive deficits as seen in ASD and ID17." (PMID 32398858, 2020). "In addition to social and cognitive deficits, Arid1b haploinsufficient mice spend considerably more time grooming than wild type mice, which is considered an appropriate measure of repetitive or stereotyped behaviors in mouse models of ASD26,27." (PMID 33594090, 2021). "Severe cognitive impairments, the primary feature of ID, are found in Arid1b+/− mice." (PMID 32398858, 2020). "Thus, complete Arid1b deletion in cortical progenitors leads to cognitive impairments in mice." (PMID 33594090, 2021). "Furthermore, Emx-Arid1b demonstrated social novelty deficits compared with their Emx-WT littermates, which may further reflect the cognitive impairments observed in the novel object recognition test, or provide further evidence of an ASD-like social phenotype." (PMID 33594090, 2021). "The smallest critical region described so far for 6q25 microdeletion have restricted to a 6q25.3 region including two protein-coding genes, ARID1B and ZDHHC14 which was considered to be responsible for the cognitive impairment and brain anomalies observed in their patients." (PMID 32380822, 2021). "Conditional homozygous deletion of Arid1b in ventral neural progenitors led to pronounced ID- and ASD-like behaviors in mice, whereas the deletion in cortical neural progenitors resulted in minor cognitive deficits." (PMID 33594090, 2021).
hypertrichosis (10 papers, 2014 to 2026). Excessive hair growth anywhere on the body. "The phenotypes caused by ARID1B mutations encompass a spectrum of features, including feeding difficulties, laryngomalacia, speech delay, motor delay, hypertrichosis, and cryptorchidism." (PMID 34775996, 2021). "For the hypertrichosis phenotype, there is a trend towards the enrichment of this phenotype in ARID1B patients (residual = 1.48) compared to all other patient groups." (PMID 34205270, 2021). "In the ARID1B population, hypertrichosis (81/130, 62%) was the only phenotype reported in the majority of individuals." (PMID 34205270, 2021). "The typical ARID1B patient has ID, feeding difficulties, laryngomalacia, speech delay, motor delay, hypertrichosis, and cryptorchidism." (PMID 30349098, 2019). "CSS is characterized by “developmental or cognitive delay, hypotonia, sparse scalp hair, distinctive facial features, aplasia or hypoplasia of the distal phalanx or nail of the fifth and additional digits, and hypertrichosis.”7 Approximately 70 ARID1B-CSS patients have been described." (PMID 30349098, 2019). "As expected, ARID1B-CSS patients more frequently displayed features associated with CSS than ARID1B-ID patients, including thick eyebrows, long eyelashes, thick alae nasi, long and/or broad philtrum, small nails and small or absent fifth distal phalanx, and hypertrichosis (p < 0.0001–0.001)." (PMID 30349098, 2019). "CSS-associated dysmorphic features, such as thick eyebrows, long eyelashes, thick alae nasi, long and/or broad philtrum, small nails and small or absent fifth distal phalanx and hypertrichosis, were observed significantly more often (p < 0.001) in ARID1B-CSS patients." (PMID 30349098, 2019). "The major differences between ARID1B-ID and ARID1B-CSS are the presence of typical dysmorphic features, including thick eyebrows, long eyelashes, hypoplastic/absent nail or distal phalanx of the fifth finger, and hypertrichosis." (PMID 34706719, 2021). "A study showed that ARID1B-CSS patients frequently exhibit typical CSS features, Facial and limb features include thick eyebrows, long eyelashes, broad nasal wings, a long and/or wide philtrum, small nails, hypoplasia or absence of the fifth distal phalanx, and hypertrichosis." (PMID 41545737, 2026).
ovarian carcinoma (10 papers, 2015 to 2025). A malignant neoplasm originating from the surface ovarian epithelium. "Several oncogenes frequently mutated in endometrial and ovarian cancer (ARID1B, ATM, BRCA1, CHD2, POLE, and PMS2) were also present in LMS." (PMID 39691991, 2025). "Concurrent ARID1A and ARID1B mutations were detected in the undifferentiated components of approximately one-quarter of dedifferentiated endometrial and ovarian carcinomas." (PMID 29890703, 2018). "Establishing the clinical relevance of ARID1A mutation and the role of ARID1B can lead to the development of more effective treatments for ovarian cancer." (PMID 29890703, 2018). "ARID1B mutations and alterations are also believed to serve as a driver of tumorigenesis in a small fraction of medulloblastoma and other solid tumors such as breast and ovarian cancers." (PMID 35660939, 2022). "A previous study reported that ARID1B knockdown suppressed growth and colony formation of ARID1A-deficient ovarian cancer cell lines." (PMID 29890703, 2018). "Specifically, the effects of ARID1A versus ARID1B loss on the accessible genome are consistent with a higher frequency of ARID1A mutations in colorectal and ovarian carcinoma." (PMID 28967863, 2017). "Indeed loss of ARID1B in ARID1A-deficient cells destabilizes the SWI/SNF complex and impairs proliferation in gastric and ovarian cancers." (PMID 32967217, 2020).
Anxiety (9 papers, 2017 to 2025). Intense feelings of nervousness, tension, or panic often arise in response to interpersonal stresses. "In the Arid1b+/- mouse model, clonazepam improves novel object recognition, social novelty and anxiety." (PMID 39740803, 2025). "This is consistent with less motoric activity in the Arid1b+/− mice and confounds a clear interpretation of anxiety-like behavior, although anxiety metrics indicate this to be a phenotype." (PMID 33757588, 2021). "Again, these results suggest PV interneuron dysfunction as a mediator of Arid1b haploinsufficiency-induced anxiety phenotypes." (PMID 32398858, 2020). "In the open field test, Arid1b+/- mice spent significantly more time in the periphery while avoiding the anxiety-provoking center." (PMID 28695822, 2017). "Arid1b heterozygous knockout (hKO) mice exhibited ASD-like traits related to social behavior, anxiety, and perseveration, in addition to associated features reported in some cases of ASD, such as reduced weight, impaired motor coordination, and hydrocephalus." (PMID 28867767, 2017). "We generated Arid1b heterozygous mice, which showed social behavior impairment, altered vocalization, anxiety-like behavior, neuroanatomical abnormalities, and growth impairment." (PMID 28695822, 2017). "These tests consistently demonstrated higher levels of anxiety-like behavior in Arid1b+/- mice compared to their WT littermates." (PMID 28695822, 2017). "In the elevated plus maze, Arid1b+/- mice spent more time in the anxiety-relieving, walled arms of the maze." (PMID 28695822, 2017). "We assessed anxiety-like behavior in Arid1b hKO mice in the elevated plus maze, light/dark transition, and open field tests." (PMID 28867767, 2017). "Arid1b hKO mice manifested anxiety-like behavior in the elevated plus maze test, and reduced exploration in the open field test." (PMID 28867767, 2017). "Clonazepam-treated Arid1b+/- mice, compared with saline-treated mice, performed better in object recognition, sociability novelty and demonstrated a decrease in anxiety-like behaviour 30–60 min post-treatment, while depression-like behaviour symptoms remained unaffected." (PMID 39740803, 2025). "In the open field assay, Dlx-Arid1b mice entered and spent significantly less time in the center area of the apparatus (9.347 s), compared to controls (33.88 s), which is indicative of anxiety-like behavior." (PMID 33594090, 2021). "AT-rich interactive domain 1B (Arid1b) haploinsufficiency mice are known to display a reduced number of cortical GABAergic interneurons and exhibit ASD-associated behaviors, including defects in social and anxiety behavior." (PMID 32982674, 2020). "Social behavior in Arid1b hKO mice might be counteracted by their increased anxiety when exposed to a novel environment or unfamiliar conspecific mouse, resulting in similar levels of social behavior to that in WT mice until they are habituated to the testing situation in social behavioral tests." (PMID 28867767, 2017). "Anxiety is a frequent comorbid condition with ASD in humans, therefore, we first examined anxiety-like behaviors in Emx-Arid1b mice by performing the elevated plus maze and open field assays." (PMID 33594090, 2021). "Because heightened levels of anxiety and depression are among the most common comorbid disorders in those with ASD, we next investigated the contribution of interneuron subtypes in these psychiatric conditions in Arid1b conditional knockout mice." (PMID 32398858, 2020). "Exogenous GH supplementation could significantly reverse the growth retardation in Arid1b+/− mice, but no improvement on abnormal behavioral phenotypes such as anxiety." (PMID 34775996, 2021). "From these results we concluded that Emx-Arid1b mice display no appreciable anxiety-like behaviors." (PMID 33594090, 2021).
colorectal cancer (9 papers, 2017 to 2025). A primary or metastatic malignant neoplasm that affects the colon or rectum. "A study in colorectal cancer cells showed that inactivation of ARID1B in ARID1A-mutated cells increases their sensitivity to IR, though only modestly." (PMID 36605718, 2022). "It is reported that depletion of ARID1B sensitizes colorectal cancer cells with ARID1A mutation to ionizing radiation." (PMID 34434896, 2021). "ARID1A-mutated colorectal cancer (CRC) cell lines are selectively sensitized to IR after siRNA mediated ARID1B depletion, as measured by clonogenic survival." (PMID 31796878, 2019). "In the current study, after confirming the synthetic lethal relationship between ARID1A and ARID1B in colorectal carcinoma proliferation, we uncovered the mechanistic basis underlying this phenomenon by examining chromatin accessibility across the genome." (PMID 28967863, 2017). "Using a panel of colorectal cancer cells that express ARID1A vs. a panel of ARID1A-deficient cells, the authors showed that downregulation of ARID1B using siRNA increased the sensitivity to IR in cells lacking both subunits." (PMID 36605718, 2022). "Here, we investigated weather knockdown of ARID1B, one of two mutually exclusive subunits within the SWI/SNF complex, can sensitize colorectal cancer cell lines mutated in the other subunit, ARID1A, to ionizing radiation (IR)." (PMID 31796878, 2019). "Synthetic–lethal relationships exist for ATPases, BRG1 and BRM, in triple negative breast cancer, for accessory subunits of the SWI/SNF complex, ARID1A and ARID1B, in colorectal cancer and CHD1 with transcriptional regulator PTEN in prostate cancer." (PMID 30755246, 2019). "Here, we investigated the effect of ARID1B knockdown on radiosensitivity in colorectal cancer (CRC) cell lines by measuring clonogenic survival after irradiation of cells with and without ARID1A mutation." (PMID 31796878, 2019). "According to the results of the pan-cancer analysis, we found that the abundances of CD4 + T cells and CD8 + T cells were significantly elevated in the mutated ARID1A, mutated ARID1B and mutated ARID2 groups, especially for colorectal cancer and gastric cancer." (PMID 35239432, 2022). "Although the effects of ARID1B knockdown are limited in comparison, our findings show that the ability of ARID1B to regulate accessibility underpins its absolute requirement for proliferation of ARID1A-deficient colorectal carcinoma cells and mutant OCCCs." (PMID 28967863, 2017). "We therefore asked whether the mechanism of ARID1A and ARID1B synthetic lethality in HCT116 colorectal carcinoma cells identified in our study is conserved in OCCCs with naturally occurring ARID1A mutations." (PMID 28967863, 2017). "Specifically, we surveyed the genes most strongly reduced by ARID1B KD in ARID1A-/- cells and identified MET, a known driver of proliferation, as a potentially crucial target of ARID1A and ARID1B in colorectal cancer." (PMID 28967863, 2017). "There is a study showing that inactivation of ARID1B in colorectal cancer cells that do not express ARID1A can further sensitize these cells to IR." (PMID 36605718, 2022). "However, alterations within ARID1B and other subunits of the BAF complex also play a role in multiple malignancies including adenoid cystic, ovarian clear cell, colorectal cancer and, gastric cancer." (PMID 33105726, 2020).
endometrial carcinoma (7 papers, 2014 to 2025). A malignant tumor arising from the epithelium that lines the cavity of the uterine body. "ARID1B mutations have been implicated in certain types of cancers, such as ovarian and breast, and—more recently—endometrial carcinomas and renal tumours." (PMID 40936011, 2025). "Using the same assay in undifferentiated endometrial carcinoma with loss of ARID1B expression shows that they have a different signature to endometrial carcinomas with intact core SWI/SNF status." (PMID 37686505, 2023). "ARID1A and ARID1B are paralog subunits that specifically nucleate the assembly of cBAF complexes and are frequently co-mutated in highly aggressive dedifferentiated/undifferentiated endometrial carcinomas (DDEC/UECs)." (PMID 41279405, 2025). "However, concurrent loss of ARID1A and ARID1B has also been detected in some cancers and in mice, dual deletion of Arid1a and Arid1b causes de-differentiation and promotes liver, squamous cell carcinoma, and endometrial cancers." (PMID 35323214, 2022). "Similarly, the homolog of ARID1A, ARID1B, is frequently mutated in endometrial cancer (9.7%) and in hepatocellular carcinoma (10.4%), but the abrogation mutation rate is <1%, which indicates that these are missense (i.e., silent) mutations which do not effect ARID1B expression." (PMID 25774356, 2014).
pancreatic cancer (7 papers, 2015 to 2023). "ARID1A-deficient pancreatic cancer cells are selectively sensitive to ARID1B knockdown and have lower viability compared to ARID1A-expressing cells." (PMID 31769422, 2019). "The role of ARID1B in hematopoiesis and leukemia is less clear, but loss of function of ARID1B has been proposed to have tumor suppressor function in lung and pancreatic cancer." (PMID 25789315, 2015). "Interestingly, mutations in the nuclear localization signal of ARID1B are observed in pancreatic cancer." (PMID 37093326, 2023). "Putative DNA binding subunits ARID1A, ARID1B, and PBRM1, enzymatic subunits SMARCA2 and SMARCA4, and ARID2 have been shown to be mutated in pancreatic cancer." (PMID 27999365, 2016). "ARID1A, ARID1B, PBRM1, SMARCA2, and SMARCA4 are all components of the SWI/SNF complexes, and were shown by genomic sequencing studies to be mutated in pancreatic cancer." (PMID 27999365, 2016). "Although not that abundant, mutations in ARID1B are also identified in neuroblastoma and pancreatic cancer." (PMID 37093326, 2023). "On tissue NGS of immunotherapy-treated, SWI/SNF-altered pancreatic cancer patients, 7 patients harbored an ARID1A alteration (77%); 2 harbored an ARID1B mutation (22%); 3 harbored a SMARCA4 mutation (33%); 1 harbored a SMARCB1 mutation (11%); and 1 harbored a PBRM1 mutation (11%)." (PMID 34375311, 2021). "In pancreatic cancer, recent whole genomic sequencing also revealed pathogenic mutations and structural variants in several epigenetic regulator genes including KDM6A, ARID1A, ARID1B, PBRM1, SMARCA2, SMARCA4, and MLL2." (PMID 27999365, 2016). "To determine whether the same might extend to other SWI/SNF subunits that we observed to be commonly mutated or deleted in pancreatic cancers, we used RNAi to knockdown SMARCA2 (the alternative enzymatic subunit), ARID1A or ARID1B (DNA targeting/specificity subunits) in normal HPDE cells." (PMID 29515757, 2018). "In summary, the current analysis suggests that a subgroup of patients with pancreatic cancer and alterations in SWI/SNF complex chromatin remodeling genes, such as ARID1A, ARID1B, PBRM1, SMARCA4, and SMARCB1, can respond to ICI." (PMID 34375311, 2021). "For instance, the pancreatic cancer cell line MIA PaCa-2 has a homozygous deletion of ARID1B and ectopic expression of ARID1B severely inhibited colony formation and anchorage independent growth of the cells." (PMID 31769422, 2019).
leukemia (6 papers, 2015 to 2025). A malignant (clonal) hematologic disorder, involving hematopoietic stem cells and characterized by the presence of primitive or atypical myeloid or lymphoid cells in the bone marrow and the blood. "In another study, where ARID1A and ARID1B were found frequently harboring loss of function mutations in acute promyelocytic leukemia, ARID1B deficiency caused a block in differentiation in this leukemia subtype." (PMID 36941700, 2023). "In addition to Myc and Bcl2, other tumor-promoting genes such as Eef2 and Myh10 were upregulated in leukemia cells, whereas tumor suppressors such as Ikzf1, Ikzf2, Arid1b, Arid2, Samhd1, Bach2, and Myo18b were downregulated." (PMID 34907175, 2021).
liver cancer (6 papers, 2016 to 2022). An epithelial or non-epithelial malignant neoplasm that arises from the liver. "Next, we investigated whether Arid1b depletion can prevent senescence in vivo and in this way contribute to liver cancer development." (PMID 27737960, 2016). "Interestingly, a significant correlation exists between the expression levels of ENTPD7 and ARID1B in several cancer types, including liver cancer." (PMID 27737960, 2016). "While ARID4A is not described in COSMIC or previous sequencing studies of liver cancer, recurrent mutations in the paralogous nucleosome remodelers ARID1A, ARID1B, and ARID2 have been previously reported in HCC21,30,35." (PMID 31796844, 2019).